CYP1A1 (cytochrome P450 family 1 subfamily A member 1)
Diseases named in the same sentence as CYP1A1 in open-access papers (continued):
Sharing a sentence is not in itself a finding about the gene and the disease.
lung carcinoma (continued). "RT‐PCR studies demonstrated significantly higher mRNA expression of polycyclic aromatic hydrocarbon (PAH)‐responsive CYP1A1 isoenzyme in the freshly prepared PBL isolated from lung cancer cases." (PMID 29460395, 2018). "In adults, effects are observed in normal lung tissue from lung cancer patients at both the CYP1A1 promoter and enhancer, which is also differentially methylated between normal tissue and lung tumor tissue." (PMID 30342560, 2018). "CYP1A1 haplotypes (in allele order CYP1A1*4, *2C, *2A); CGC and CG associated with increased risk of lung cancer confirming CYP1A1 polymorphisms as minor risk factor for NSCLC." (PMID 28074113, 2017). "Among the variety of xenobiotic metabolising enzymes, CYP1A1, GSTM1 and GSTT1 have been implicated to modulate the risk of lung cancer because of their potential involvement in carcinogenesis metabolism." (PMID 27090234, 2016). "Lung cancer patients who smoked and having CYP1A1 m1 T/C, C/C and CYP1A1 m2 A/G, G/G and GSTT1 null (−/−) genotypes were at higher risk compared to the controls." (PMID 27090234, 2016). "In our study, the combinations of two (CYP1A1 m2 and GSTM1) or three (CYP1A1 m1, CYP1A1 m2 and GSTM1/GSTT1) genotypes had a profound effect on susceptibility to lung cancer up to 14-fold depending on the genotypic interaction." (PMID 27090234, 2016). "CYP1A1, GSTM1, GSTP1 and GSTT1 polymorphisms and their association to lung cancer in a cohort of North Indian population was reported." (PMID 27090234, 2016). "Patients who were non-smokers and having a CYP1A1 m1 (T/C) (OR 1.82, 95 % CI 1.08, 3.07) and CYP1A1 m2 (A/G) (OR 12.39 95 % CI 6.53, 23.51) genotypes had an increased lung cancer." (PMID 27090234, 2016). "Heterozygous and homozygous minor CYP1A1 m2 genotypes were on the higher side in Chilean lung cancer patients." (PMID 27090234, 2016). "It has been shown that CYP1A1 is hypermethylated in lung cancer samples compared to normal lung samples, and this was associated with reduced mRNA levels." (PMID 22768131, 2012). "We evaluated the impact of polymorphisms detected in 4 in Phase I and Phase II metabolism genes (CYP1A1 MspI T6235C, GSTM1 present/null, GSTT1 present/null and GSTP1 Ile105Val) on the risk of developing lung cancer." (PMID 23013535, 2012). "We evaluated the main effects of phase I/phase II xenobiotic metabolism genes (CYP1A1, GSTM1, GSTP1 and GSTT1) in relation to lung cancer susceptibility using univariate as well as multivariate statistics." (PMID 23013535, 2012). "CYP1A1*2A and EPHX1 His139Arg polymorphisms were associated with increased risk to lung cancer in dominant genetic model, whereas EPHX1 Tyr113His and SULT1A1 Arg213His imparted reduced risk in recessive genetic model." (PMID 22206016, 2011). "In this present study, we propose to research the combined effects of CYP1A1 gene and GSTM1 gene polymorphism and their risks to lung cancer." (PMID 21859547, 2011). "Cytochrome P450A1 (CYP1A1) gene and glutathione S-transferase M1 (GSTM1) gene both have single nucleotide polymorphisms and effects on lung cancer." (PMID 21859547, 2011). "We discovered through our meta-analysis that the combined effects of CYP1A1 gene and GSTM1 gene polymorphism are significantly associated with an increased risk to lung cancer." (PMID 21859547, 2011). "Elevated CYP1A1 inducibility is associated with pulmonary PAH-related DNA adduction and high lung cancer risk." (PMID 20804547, 2010). "A recent pooled analysis also suggested that genetic polymorphisms in CYP1A1 and GSTM1 are associated with lung cancer risk among Asian populations." (PMID 20704749, 2010).
lung carcinoma (continued). "The findings suggest that smoking related biological pathways leading to the development of lung cancer involve not only hypermethylations of p16, DAPK and RARβ promoters but also genetic polymorphisms of CYP1A1 and GSTM1 genes." (PMID 20704749, 2010). "Many studies have reported that polymorphism in CYP1A1 as well as in GSTM1, or combination effect of both, have been associated with different types of cancer risk including human lung cancer." (PMID 20704749, 2010). "The study examined the relationship between polymorphisms in CYP1A1 and GSTM1 and aberrant methylation of p16, DAPK and RARβ in lung cancer." (PMID 20704749, 2010). "An early study from Japan reported the combined effects of CYP1A1 MspI genotype and deficient GSTM1 in lung cancer (OR = 16.00), but only at a low-dose level of cigarette smoking." (PMID 20704749, 2010). "Increased pulmonary CYP1A1 activity is associated with increased DNA adducts from PAH exposure and elevated risk of lung cancer." (PMID 19650907, 2009). "In the present study, the possibility of association of CYP1A1 and microsomal epoxide hydrolase (HYL1) genetic polymorphisms with lung cancer was examined among 132 lung cancer patients and 259 controls in Taiwan." (PMID 10732758, 2000). "A combination of susceptible CYP1A1 and HYL1 genotypes was found to be highly associated with lung cancer, especially with SCC (OR 6.76; 95% CI 2.29–19.10)." (PMID 10732758, 2000). "For example, polymorphisms in cytochrome P450 1A1 (CYP1A1) and glutathione S-transferase M1 (GSTM1) may contribute to the increased risk of females for lung cancer." (PMID 39107837, 2024). "Among polymorphisms in the cytochrome P450 genes, one, Ile462Val, in the CYP1A1 gene, is associated with lung cancer risk in never-smokers, whereas the other, Leu432Val, in the CYP1B1 gene, carries a risk of cancer independently of smoking status." (PMID 36817482, 2023). "The data revealed that XRCC1 and CYP1A1 were the targets of miR-486-3p in lung cancer cells." (PMID 33500536, 2022). "In addition, overexpressed of XRCC1 and CYP1A1 reversed the inhibitory effect of miR-486-3p mimic on lung cancer cells, which further confirmed the targeted relationship among miR-486-3p and XRCC1 and CYP1A1." (PMID 33500536, 2022). "Meta-analysis performed after excluding the study revealed a nominal association of rs1048943/CYP1A1 [AG + GG vs AA: OR = 1.67, 95% C.I. = 1.18─2.25; p = 0.003] with overall lung cancer without any significant heterogeneity." (PMID 34272429, 2021). "The association of variants with different histological subtypes of lung cancer revealed del1/GSTT1 to be associated with lung adenocarcinoma, rs4646903/CYP1A1 with lung squamous cell carcinoma while rs1048943/CYP1A1 with both lung adenocarcinoma and lung squamous cell carcinoma." (PMID 34272429, 2021). "Thus, the results indicate a potential role of rs1048943/CYP1A1 in a specific histological subtype of lung cancer, indicating the disease's genetic heterogeneity and variability." (PMID 34272429, 2021). "CYP1A1, or cytochrome P4501A1, is a lung cancer susceptibility gene." (PMID 30342560, 2018). "A study similar to ours emphasized the important role of xenobiotic metabolizing enzymes in several cancer types like bladder and lung cancer or leukemia; cytochrome (CY) P450 enzymes such as CYP1A1 are activated in the case of the smoking group as compared to never smokers." (PMID 30041465, 2018). "CYP1A1-rs1048943 GG+AG genotype, GSTM1 deletion genotype, mEH-rs1051740 mutant genotype, XRCC1-rs1799782 TT+CT genotype, XRCC1- rs25489 GG genotype showed significant correlations with lung cancer risk increased." (PMID 29212267, 2017). "Our subgroup analysis also found that some variants showed significant associations with lung cancer risk in smokers but not in non-smokers, for example CYP1A1 rs4646903 and GSTP1 rs1695." (PMID 28827732, 2017).
lung carcinoma (continued). "Combined variant CYP1A1*2C/ CYP1A1*4 associated with higher risk of lung cancer specially NSCLC among non-smokers." (PMID 28074113, 2017). "The association between CYP1A1 and GSTM1 polymorphisms in lung cancer was reported." (PMID 27090234, 2016). "CYP1A1, GSTM1 and GSTT1 polymorphisms and the association with lung cancer in the South Indian population (patients reporting to a specific hospital in Thiruvananthapuram, the capital city of Kerala state) was reported, suggesting the risk in the specific population of that state." (PMID 27090234, 2016). "The impact of CYP1A1 m1, CYP1A1m2, GSTM1 and GSTT1 gene polymorphisms on superoxide dismutase activity, Glutathione peroxidase activity, MDA and 8-OHdG levels were assessed between controls and lung cancer patients." (PMID 27090234, 2016). "Furthermore, several studies have correlated the induction of CYP1A1 enzymatic activity with the development of lung cancer." (PMID 23509697, 2013). "We investigated if the individual and/or combined modifying effects of the CYP1A1 MspI T6235C, GSTM1 present/null, GSTT1 present/null and GSTP1 Ile105Val polymorphisms are related to the risk of developing lung cancer in relation to tobacco consumption and occupation in Asturias, Northern Spain." (PMID 23013535, 2012). "Our findings suggest that gefitinib metabolism in lung cancer cells, elicited by CYP1A1 activity, might represent an early assessment of gefitinib responsiveness in NSCLC cells lacking activating mutations." (PMID 22111840, 2011). "Currently, however, the risk of lung cancer due to the CYP1A1 and GSTM1 genes has no clear evidence." (PMID 21859547, 2011). "Also, another analysis indicated a possible interaction between the CYP1A1*2A allele and GSTM1 deletion on lung cancer risk in Caucasians." (PMID 20704749, 2010). "In this large population-based case-control study of lung cancer we have observed that EPHX1, CYP1A1, CYP1B1 and CYP2A6 genes may play a role in lung cancer susceptibility." (PMID 19479063, 2009). "Furthermore, one of that category's highest scoring genes, CYP1A1, is expressed in primary lung cancer samples in a manner highly correlated with tobacco dose." (PMID 17845722, 2007). "Moreover, we observed a higher level of CYP1A1 RNA editing in the highly metastatic lung cancer cell line 95D compared with other cell lines, which suggested that there could be a positive correlation between CYP1A1 overediting and tumor progression." (PMID 40175891, 2025). "Additionally, quercetin found in apples might arrest cytochrome P450 enzymes in lung cancer, such as cytochrome P450 family 1 subfamily A member 1 (CYP1A1), which could be responsible for the induction of carcinogenesis." (PMID 39408274, 2024). "The glutathione S-transferase GSTT1 null genotype, if combined with the CYP1A1 variant, may confer an increased risk of lung cancer in never smokers." (PMID 36817482, 2023). "Furthermore, subgroup analysis of 4 variants stratified by smoking status revealed rs1048943 of the CYP1A1 gene to be significantly associated with lung cancer in smokers and non-smokers." (PMID 34272429, 2021). "The RE model is known to have lower power, which could potentially explain the lack of significant association of rs1048943/CYP1A1 with overall lung cancer." (PMID 34272429, 2021). "Smoking was identified as a predominant risk factor and CYP1A1*2A polymorphism significantly associated with increased lung cancer risk (OR = 1.69; 95% CI = 1.11–2.59, p = 0.01), whereas CYP1A1*2A and *2C and Ile105Val imparted increased risk in non-smokers only." (PMID 28074113, 2017). "Therefore, CYP1A1 activation might be the reason for the reduced estradiol and thereby increased expression of IL-6 in lung cancer." (PMID 26316937, 2012).
lung carcinoma (continued). "An association between CYP1A1 polymorphisms and lung cancer was first reported by Kawajiri and co-workers in 1990 among an Asian study population, after which many studies analyzed the influence of CYP1A1 polymorphisms on lung cancer risk; no clear consensus, however, was reached." (PMID 22952673, 2012). "CYP1A1 is a phase I enzyme involved in the metabolic activation of aromatic amines and PAH and may affect the metabolism of environmental carcinogens and alter susceptibility to lung cancer." (PMID 19440419, 2009). "More recently, the circRNA circFLNA has been found to promote lung cancer progression by acting as a sponge of miR-486-3p and thus regulating the XRCC1 (X-ray Repair Cross Complementing 1) and CYP1A1 (Cytochrome P450 Family 1 Subfamily A Member 1) genes." (PMID 38501058, 2024). "Next, we detected the expression of AhR pathway genes (IDO1, AhR, CYP1A1, and CYP1B1) in SARS-CoV-2–infected and mock-infected human lung cancer cells (H1299 and Calu-3)." (PMID 37256962, 2023). "The results in this study revealed that circFLNA acted as a sponge of miR-486-3p to promote the proliferation, migration, and invasion of lung cancer cells via regulating XRCC1 and CYP1A1 in vitro and in vivo." (PMID 33500536, 2022). "In conclusion, circFLNA acted as a sponge of miR-486-3p to promote the proliferation, migration, and invasion of lung cancer cells in vitro and in vivo by regulating XRCC1 and CYP1A1." (PMID 33500536, 2022). "Therefore, genetic polymorphisms of CYP1A1-rs1048943, GSTM1, GSTT1, mEH-rs1051740 and XRCC1(rs1799782, rs25489), methylation of p16 and RASSF1A gene, and telomere length were analyzed in peripheral blood both from lung cancer patients and health controls to explore their correlation." (PMID 29212267, 2017). "In fact, the lower expression of CYP1A1 among never smokers and higher expression among current smokers in association with the SNPs at chr15q24.1 was consistent with the observed protective effect for lung cancer among never smokers and risk among smokers in association with variants in CYP1A1/A2." (PMID 19479063, 2009). "The simultaneous induction of CYP1A1 and CYP1B1 in both types of lung cells obtained from BAL and pulmonary epithelial cells after smoking cigarettes, as found in the present study, may therefore enhance an individual susceptibility for chemically induced lung cancer." (PMID 17107849, 2006). "The combination NAT2 slow-CYP1A1 rapid acetylator were at highest risk for lung adenocarcinoma in non-smoking females or the NAT2-CYP1A1 rapid acetylators may also predispose higher risk to lung cancer in female never smokers." (PMID 16827944, 2006). "Involvement of highly significant DEGs including SLCO1A2, OLFM4, RTKN2, CYP1A1, and MUC5AC plays a key role in rheumatoid arthritis development.Highly significant DEGs including OLFM4, RTKN2, CYP1A1, MUC5AC, CYP2A6, PCK1, and PITX1 have been reported to encourage the development of lung cancer." (PMID 38137330, 2023). "Furthermore, miR-486-3p mimic reversed the effect of circFLNA overexpression on promoting lung cancer cells and tumors and regulating the expressions of miR-486-3p, XRCC1, CYP1A1, and metastasis/apoptosis/proliferation-related factors." (PMID 33500536, 2022). "Results of our study indicate that CYP1A1 polymorphisms rather than GSTM1 polymorphisms and smoking contribute to the higher risk of lung cancer." (PMID 27090234, 2016). "For instance, under a higher OR with no heterogeneity, people with CYP1A1 (mt/mt) and GSTM1 null genotype should pay more attention to avoiding exposure to harmful environmental factors associated with lung cancer." (PMID 25036724, 2014). "The results of the analysis of gene-gene interactions of CYP1A1 MspI T6235C, GSTM1 present/null, GSTT1 present/null and GSTP1 Ile105Val polymorphisms in lung cancer risk indicate that these genes do not interact in lung cancer development." (PMID 23013535, 2012).
lung carcinoma (continued). "Distribution of CYP1A1 and EPHX1 haplotype frequency among lung cancer cases and controls." (PMID 22206016, 2011). "Among non-smokers CYP1A1*2A and GSTP1 Ile105Val were the most important polymorphisms identified for lung cancer development." (PMID 22206016, 2011). "Our study included 8 SNPs from the CYP1A1/A2 region not previously studied in case-control studies of lung cancer, and some of these SNPs were not included in the platforms used for recent genome-wide association studies (GWAS)." (PMID 19479063, 2009). "The cumulative number of variants from CYP1A1 and CYP1A2 was in fact associated with a significant risk for lung cancer in ever smokers and a protective effect in never smokers, with a highly significant smoking-genotype interaction." (PMID 19479063, 2009). "Excluding CYP1A1, FRMD4A and GF1 CpGs did not affect the association of Score-15 and Score-19 with lung cancer risk, and only the FRMD4A CpG score was associated with lung cancer risk." (PMID 39544416, 2024). "MDR analysis identified two distinct predictor models for the risk of lung cancer in smokers (tobacco chewing, EPHX1 Tyr113His, and SULT1A1 Arg213His) and non-smokers (CYP1A1*2A, GSTP1 Ile105Val and SULT1A1 Arg213His) with testing balance accuracy (TBA) of 0.6436 and 0.6677 respectively." (PMID 22206016, 2011). "However, the impact of CD exposure on lung cancer in miners is difficult to interpret because most of them are smokers and consequently have exposure to carcinogenic PAHs in the cigarette smoke, which would normally induce cytochrome P4501A1 (CYP1A1) activity." (PMID 19650907, 2009). "Cigarette smoke was reported to induce CYP1A1 and CYP1B1 expressions in lung tissue of smokers and of lung cancer patients (both smokers and non-smokers), which correlates with increased levels of BPDE and DNA adducts." (PMID 38982523, 2024). "Although many genes, such as CYP1A1, ERCC2, and L10, have been confirmed to relate to nonsmoking lung cancer, the mechanism related to nonsmoking female lung cancer patients is not clear." (PMID 34671675, 2021).